DYRK3 (dual specificity tyrosine phosphorylation regulated kinase 3)
Diseases named in the same sentence as DYRK3 in open-access papers (continued):
Sharing a sentence is not in itself a finding about the gene and the disease.
ovarian carcinoma (1 paper, 2024). A malignant neoplasm originating from the surface ovarian epithelium. "The intricate associations observed underscore the multifaceted impact of DYRK3 on immune cell populations, providing crucial insights for understanding the immune landscape in ovarian cancer." (PMID 38529261, 2024). "While DYRK3 has been implicated in various malignancies, its specific role in ovarian cancer remained largely unexplored." (PMID 38529261, 2024). "Future research should focus on unraveling the intricate signaling pathways associated with DYRK3 in ovarian cancer and exploring its potential interactions with the tumor microenvironment." (PMID 38529261, 2024). "DYRK3 knockdown using shRNAs demonstrated substantial cellular repercussions in ovarian cancer cells, compared to mock controls and scrambled-shRNA controls." (PMID 38529261, 2024). "The in vivo impact of DYRK3 knockdown on ovarian cancer growth was assessed through subcutaneous xenograft experiments with CAOV3 and OVCAR-3 cells." (PMID 38529261, 2024). "The in vivo data provides compelling evidence of DYRK3's pivotal role in promoting ovarian cancer growth in an in vivo microenvironment." (PMID 38529261, 2024). "In vivo experiments with DYRK3-knockdown cell lines validated these findings, demonstrating a notable restriction in the growth of ovarian cancer xenografts." (PMID 38529261, 2024). "As we delve into this exploration, we anticipate shedding light on DYRK3's significance and paving the way for novel therapeutic avenues in the management of ovarian cancer." (PMID 38529261, 2024). "This study establishes a compelling foundation for further research into DYRK3's intricate role and therapeutic potential in ovarian cancer treatment." (PMID 38529261, 2024). "Additionally, Matrigel-Transwell assays demonstrated impaired invasion capacities in both cell lines upon DYRK3 knockdown, suggesting a potential regulatory role of DYRK3 in the invasive behavior of ovarian cancer cells." (PMID 38529261, 2024). "While our findings contribute to the growing body of knowledge on DYRK3 in cancer, ongoing research is essential to fully comprehend its intricate functions, paving the way for targeted therapies and personalized treatment approaches in ovarian cancer." (PMID 38529261, 2024). "As we unravel the complexities surrounding DYRK3, our work not only contributes to the understanding of SOC pathogenesis but also unveils new prospects for targeted therapeutic interventions, holding promise for improved outcomes in ovarian cancer management." (PMID 38529261, 2024). "Nevertheless, DYRK3's role in other malignancies, specifically in ovarian cancer is not well characterized." (PMID 38529261, 2024). "By analyzing the correlation between DYRK3 and EMT-related genes in TCGA-ovarian cancer dataset, we observed a positive correlation between DYRK3 with FLNB and SOX9, both of which had been well acknowledged as oncogenic molecules in tumorigenesis and cancer progression." (PMID 38529261, 2024).
serous ovarian cancer (1 paper, 2024). "Experimental investigations involved DYRK3 knockdown in serous ovarian cancer cell lines (CAOV3 and OVCAR-3) through a shRNA strategy, revealing substantial decreases in cell growth and invasion capabilities." (PMID 38529261, 2024). "Utilizing the TCGA dataset, our analysis uncovered a compelling correlation between DYRK3 expression and immune cell infiltration in ovarian serous cancer." (PMID 38529261, 2024). "Our study sheds light on the prognostic significance of DYRK3 in serous ovarian cancer and unveils its potential role in modulating immune cell infiltration." (PMID 38529261, 2024). "Our study delves into the multifaceted role of DYRK3 in serous ovarian cancer (SOC), providing novel insights into its potential as a prognostic marker and therapeutic target." (PMID 38529261, 2024). "This research endeavors to bridge the existing knowledge gap by comprehensively investigating the expression of DYRK3 in serous ovarian cancer patients." (PMID 38529261, 2024).
tumor (13 papers, 2018 to 2025). "While the tumor-modulatory role of DYRK3 has been demonstrated in a limited number of recent studies, the detailed mechanisms underlying how DYRK3 affects the development of various types of cancers and its downstream substrates have not been extensively investigated." (PMID 38519031, 2024). "The positive correlation of DYRK3 with multiple immune cells like Tcm cells and NK cells, and its negative association with Th1 and Th2 cells, provides a hint into the complexity of the tumor microenvironment influenced by this kinase." (PMID 38529261, 2024). "We recently demonstrated that DYRK3 is essential for tumor cell motility: altered DYRK3 levels inhibit cell migration and Matrigel invasion." (PMID 41325334, 2025). "Beyond its adverse prognostic implications, DYRK3 knockdown exhibited promising therapeutic potential by impeding cancer progression and potentially influencing the tumor immune microenvironment." (PMID 38529261, 2024). "Similar to the action of DYRK3, p38δ can phosphorylate p62 at T269 and S272, and p38δ is known to promote skin carcinogenesis by facilitating the formation of a proinflammatory microenvironment that supports epidermal hyperproliferation and tumorigenesis." (PMID 38519031, 2024). "Taken together, these results suggest that phosphorylation of p62 at T269 by DYRK3 promotes SK-Mel-28 tumor growth in vivo." (PMID 38519031, 2024). "Bioinformatics analyses further hinted at DYRK3's involvement in modulating the tumor immune microenvironment." (PMID 38529261, 2024). "Within this context, the dual-specificity tyrosine phosphorylation-regulated kinase 3 (DYRK3) has emerged as a potential key player with implications for prognosis and tumor progression." (PMID 38529261, 2024). "The inhibitory effects of DYRK3 knockdown on key cellular processes and in vivo tumor growth emphasize its promise as a therapeutic target." (PMID 38529261, 2024). "Among them, DYRK3 has both an oncogenic and tumor suppressor role, depending on the phosphorylation targets." (PMID 38519031, 2024). "Growth curves of established xenografts revealed a substantial inhibition in tumor growth upon DYRK3 silencing." (PMID 38529261, 2024). "In mice treated with the DYRK3 inhibitor, there was a slight increase in tumor sizes at certain intervals, resulting in a 1.6 times larger size by the 8th week compared to the control group, a difference that was statistically significant (p < 0.01)." (PMID 38139175, 2023). "Subsequent experiments using tumor samples from the xenograft mouse models revealed significant suppression of DYRK3, PAICS, and Ki-67 proteins in the mice treated with the DYRK3 inhibitor and the combined treatment, relative to the control mice." (PMID 38139175, 2023). "On the other hand, studying the expression directly within the tumor tissue allows for a more localized and precise understanding of how DYRK3 interacts and influences the tumor environment, cell growth, and proliferation." (PMID 38139175, 2023). "Investigating the mRNA expression in normal vs. tumor samples, DYRK3 and DYRK4 were found to have significantly lower methylation level compared to the control in COAD." (PMID 35454940, 2022). "Consistent with what was observed with our RNA seq from UALCAN web tool analysis (F2-F3), the expression level of DYRK3 and 4 (z-score = or >1) were high in the majority of the tumor samples." (PMID 35454940, 2022). "This difference is reminiscent of the DYRK kinase family, in which DYRK1A usually acts as an oncogene, while DYRK1B and DYRK3 inhibit tumor progression." (PMID 35092699, 2022). "The expression of DYRK1A and DYRK3 expression correlated with immune-infiltrating cells in the tumor microenvironment and was upregulated in MSI subtypes, pointing to their potential role as biomarkers for immunotherapy." (PMID 35454940, 2022).
tumor (continued). "The diverse roles that DYRK3 plays in tumor progression was also recently supported using data from a proteomic database, with targets of DYRK3 that included CREB and H3F3A." (PMID 33804169, 2021). "Taken together, these results suggest DYRK3 knockdown can reverse many irradiation-induced GBM tumor cell migration and invasion features." (PMID 33804169, 2021). "Our findings collectively illuminate DYRK3 as a pivotal tumor-promoting oncogene in SOC." (PMID 38529261, 2024). "RT-qPCR analysis from tumor RNA samples reflected the efficient downregulation of DYRK3 by doxycycline treatment, thus confirming a critical and previously unrecognized role for this kinase in NB cell proliferation and in vivo tumor growth." (PMID 38255303, 2024). "DYRK3 specifically has oncogenic or tumor-suppressive roles based on its phosphorylation target." (PMID 33804169, 2021). "Thus, combinations of chemotherapeutics that target SGs with Hsp90 and DYRK3 inhibitors could provide enhanced anti‐tumor activity, providing a promising new direction for cancer therapy." (PMID 33738926, 2021). "Moreover, DYRK3 was proposed as a specific early-stage tumor driver in gastric cancer." (PMID 32751160, 2020). "In this study, our focus was to assess the expression and relationship between DYRK3 and PAICS in human tumor xenograft samples with varying degrees of radioresistance and radiosensitivity." (PMID 38139175, 2023). "Nevertheless, the specific role of DYRK3, a vital member of the DYRK family, as a tumor suppressor or promoter, and its potential involvement in cancer, remain largely unexplored." (PMID 38139175, 2023). "Wound healing and tumor sphere formation experiments demonstrated slower healing of scratch wounds and the suppression of OSCC cell stemness in response to DYRK3 depletion at both 24 and 48 h." (PMID 38139175, 2023). "In conclusion, our findings provide compelling evidence that overexpressing DYRK3 in OSCC cells significantly enhances their oncogenic properties, especially in relation to colony formation, migration, invasion, and tumor sphere generation." (PMID 38139175, 2023). "In correlation with DYRK3 and DYRK4 overexpression in tumors vs. normal, promotor methylation was significantly decreased in different tumor stages compared to normal." (PMID 35454940, 2022). "Interestingly, we observed that increased DYRK3 activity specifically enhances the phosphorylation of the PMAP scaffold protein Liprin-α1, a promoter of tumor cell migration and focal adhesion turnover." (PMID 41325334, 2025). "Our study not only highlights DYRK3 as a tumor-promoting oncogene in SOC but also elucidates its potential as a therapeutic target by demonstrating the inhibitory effects of DYRK3 knockdown on cell viability, invasion, and in vivo tumor growth." (PMID 38529261, 2024). "This points to DYRK3 being not just a prognostic marker but potentially a mechanistic driver of tumor progression." (PMID 38529261, 2024). "Furthermore, we conducted an in vivo study to affirm the impact of DYRK3 and PAICS on tumor growth and radiotherapy resistance, focusing particularly on the role of DYRK3 in the radiotherapy resistance pathway." (PMID 38139175, 2023). "However, the introduction of DYRK3 in HCC cells led to a marked reduction in tumor growth and metastasis in xenograft tumor models." (PMID 38139175, 2023). "Both DYRK1A and DYRK2 showed a significantly lower expression in READ tumor vs. normal tissues, whereas DYRK1B, DYRK3 and DYRK4 had no significant change in expression." (PMID 35454940, 2022). "Our analysis of the TCGA data did not reveal any specific trend for DYRK3, which is under-expressed in breast (BRCA), kidney (KIHC), lung (LUAD and LUSC), prostate (PRAD) and thyroid (THCA) tumor cohorts and overexpressed in colon (COADREAD), HNSCC, kidney (KIRC) and stomach (STAD) cancer tissues." (PMID 32751160, 2020).
cancer (11 papers, 2020 to 2025). A tumor composed of atypical neoplastic, often pleomorphic cells that invade other tissues. "Finally, a reduction in the DYRK3 protein was recently described in HCC biopsies relative to normal tissue, and low DYRK3 levels were associated with a poor prognosis in this type of cancer." (PMID 32751160, 2020). "The dual-specificity tyrosine phosphorylation-regulated kinase 3 (DYRK3) is an intriguing molecule in controlling the phase transition of membraneless organelles and plays critical roles in cancer biology." (PMID 38529261, 2024). "Their analysis of the The Cancer Genome Atlas database revealed a significant elevation in DYRK3 mRNA levels in GBM patients compared to normal controls." (PMID 38519031, 2024). "According to the analysis of The Cancer Genome Atlas data through Gene Expression Profiling Interactive Analyses, the expression level of DYRK3 was significantly increased in melanoma cancer tissues compared with normal skin tissues." (PMID 38519031, 2024). "Our research indicates that DYRK3 expression is notably higher in human cancer tissues than in healthy ones." (PMID 38139175, 2023). "In cancer, DYRK3 was proposed to act in parallel with DYRK1A to promote cell survival under stressful conditions by phosphorylating nicotinamide adenosine dinucleotide (NAD)-dependent deacetylase SIRT1." (PMID 35454940, 2022). "Our findings align with emerging research suggesting DYRK3 as a crucial player in cancer biology." (PMID 38529261, 2024). "To further verify this hypothesis and, if that is the case, to identify additional phosphorylation target(s) of DYRK3, we first analyzed the relationship between the expression of DYRK3 and various cancer types." (PMID 38519031, 2024). "Additionally, the precise molecular mechanisms through which DYRK3 modulates immune cell infiltration and influences cancer progression require further elucidation." (PMID 38529261, 2024). "Furthermore, our neuro sphere formation assays suggested that elevating DYRK3 levels fortified the stemness of OSCC cells, a quality closely associated with the self-renewal and differentiation capacities of cancer cells." (PMID 38139175, 2023). "A few studies have been conducted to investigate the role of DYRK3 and 4 in cancer." (PMID 35454940, 2022). "Our hypothesis posits that the cancer-inducing role of PAICS/DYRK3 could be instrumental in fostering radioresistance and metastasis in OSCC by boosting the functionality of the purinosome, which in turn enhances the stemness, tumorigenicity, and drug resistance of OSCC." (PMID 38139175, 2023). "Considering that cancer cells are characterized by a high protein synthesis rate, part of the efficacy of the Hsp90 inhibitors may depend on their ability to destabilize DYRK3, thereby promoting SG persistence and perturbing translation restoration after stress." (PMID 33738926, 2021). "Another study showed DYRK3-mediated direct phosphorylation of PRAS40 and mTORC1 activation, demonstrating the strong potential for DYRK3 in cancer signaling regulation." (PMID 33804169, 2021). "DYRK3 may be an upstream regulator of DRP1 and may be a target of chemical inhibitors such as Harmine and GSK-626616, which were proposed as novel and promising cancer treatment strategies." (PMID 33804169, 2021).
infection (1 paper, 2022). The state of being infected such as from the introduction of a foreign agent such as serum, vaccine, antigenic substance or organism. "In our infection model, OC43 affected the rate of SG assembly and did not increase the rate of SG dissolution or levels of SG disassembly-promoting factors such as chaperones HSP90α/β or the dual specificity kinase Dyrk3." (PMID 36534661, 2022).
DYRK3 also shares sentences with these, for which no sentence is quoted: brain ischemia (1 paper); cholangiocarcinoma (1); colorectal cancer (1); gastric cancer (1); hereditary spherocytosis (1); influenza infection (1); lymphoma (1); neurodegenerative disease (1); osteosarcoma (1); skin cancer (1).